RFX4-AS1 (RFX4 antisense RNA 1)
Synonyms: uc.346; LOC100505978
Gene: Long non-coding RNA gene on chromosome 12 (106,488,804 to 106,774,956, reverse strand). Ensembl gene ENSG00000257545.
Diseases named in the same sentence as RFX4-AS1 in open-access papers:
RFX4-AS1 is named in the same sentence as 11 diseases in open-access papers, as found by Europe PMC text mining. Sharing a sentence is not in itself a finding about the gene and the disease.
RFX4-AS1 shares sentences with these, for which no sentence is quoted: adenocarcinoma (2 papers); adenoma (2); in situ carcinoma (2); tumor (2); carcinoma (1); colon cancer (1); colonic tumor (1); colorectal adenocarcinoma (1); colorectal adenoma (1); colorectal cancer (1); hyperplastic polyp (1).